GPX3 (glutathione peroxidase 3)
Diseases named in the same sentence as GPX3 in open-access papers (continued):
Sharing a sentence is not in itself a finding about the gene and the disease.
Obesity (continued). "The other four haplotypes were associated with obesity when classification was based on BFP—one of them in GPX3 in a protective direction and the others in PON genes conferring obesity risk." (PMID 32752212, 2020). "The other four haplotypes were associated with obesity when it was classified by BFP; one of them in GPX3, two others in PON1, and the last one in PON2 and PON3." (PMID 32752212, 2020). "Six haplotypes were significantly associated with obesity; two of them (one in GPX3 and the other one in GPX5 and GPX6) showed this association in a protective direction when obesity was classified by BMI." (PMID 32752212, 2020). "Obesity-induced reduction of adipose tissue GPX3 expression was also shown to play a significant role in proinflammatory reaction through induction of both local and systemic oxidative stress." (PMID 32344656, 2020). "It is also notable that SAT GPX3 expression was shown to be higher as compared to omental depot in lean subjects, whereas obesity ameliorated this difference." (PMID 32344656, 2020). "Another study that supports GPX3 activity against obesity showed that estrogen receptor α activates GPX3 transcription and that this mediates its fat mass reducing effects." (PMID 24562334, 2014). "For several adipokines (ANGPTL3, DLL1, chemerin, clusterin, leptin, Nampt, resistin, GPX3), we identified a close relationship with parameters of obesity (BMI, waist circumference, body fat mass), but also inflammation (hsCrP)." (PMID 24968098, 2014). "In addition, in the adipose tissue where GPX3 is highly expressed, lower GPX3 expression was correlated with insulin resistance, obesity, inflammation and circulating levels of lipids and glucose." (PMID 40895323, 2025). "Thus, the inability of selenite supplementation to enhance GPx3 in established obesity can explain why obesity prevents a supplemented Se-induced insulin-sensitizing effect in adipose tissue." (PMID 35624726, 2022). "Moreover, supplementation with CTE prevented the obesity-induced decrease in the gene expression of the antioxidant enzymes GPX-3, GSR and SOD-1, and increased the mRNA levels of endothelial nitric oxide synthase (eNOS) in arterial tissue." (PMID 36009292, 2022). "Obesity was associated with an upregulation in the gene expression of IL-1β (p < 0.05), IL-6 (p < 0.01) and NOX-4 (p < 0.05), and with a downregulation in the mRNA levels of the antioxidant enzymes GPX-3 and SOD-1 (p < 0.01 for both) in aortic tissue." (PMID 36009292, 2022). "The rs922429 GPx3 variant had not been previously studied, so this is the first study showing association with obesity as a protective factor." (PMID 32752212, 2020). "These authors did not measure GPx-3 activity but the changes in weight and gene expression support our findings and those from other cohorts that obesity and the metabolic syndrome is associated with an increase in GPx-3 activity." (PMID 31817851, 2019). "Since ANGPTL3, DLL1 and GPX3 are found in the same cluster, our data may stimulate further research characterizing the potential role of ANGPTL3, DLL1 and GPX3 in obesity, altered glucose metabolism and inflammation." (PMID 24968098, 2014). "Adiponectin and GPX-3 are listed in blue because their circulating levels are lower in obesity." (PMID 20508843, 2010). "However, findings regarding the relationship between GPX3 expression and obesity remain mixed." (PMID 38927092, 2024). "In summary, we have shown that selenite protects against palmitate-induced insulin resistance with increased GPx3 and IR expression in vitro, while the selenium intervention was not successful in modulating plasma selenium status and GPx3 expression under conditions of obesity in vivo." (PMID 35624726, 2022). "DC only attenuated the obesity-induced downregulation of NOX-4 (p < 0.05), whereas DCE also prevented the alterations in the mRNA levels of NOX-4 (p < 0.01), GSR (p < 0.05) and GPX-3 (p < 0.01)." (PMID 36139877, 2022).
Obesity (continued). "Obesity induced a significant decrease in the mRNA levels of NOX-4 (p < 0.05), GSR (p < 0.01), GPX-3 (p < 0.05), and SOD-1 (p < 0.05)." (PMID 36139877, 2022). "On the contrary, DCT downregulated the obesity-induced overexpression of GSR (p < 0.05) and increased the mRNA levels of GPX-3 (p < 0.05)." (PMID 36139877, 2022). "DC attenuated the reduction in the gene expression of GSR and SOD-1 (p < 0.05 for both), whereas DCE, DCT, and DCTE completely prevented the obesity-induced reduction in the mRNA levels of NOX-4, GSR, GPX-3 and SOD-1 (p < 0.05)." (PMID 36139877, 2022). "Finally, DCTE reduced the obesity-induced alterations in the gene expression of GSR (p < 0.01), SOD-1 (p < 0.05) and PGC-1α and up-regulated the mRNA levels of GPX-3 (p < 0.05)." (PMID 36139877, 2022). "Finally, DCT attenuated the obesity induced-changes in the gene expression of NOX-1 (p < 0.05), NOX-4 (p < 0.01), and GPX-3 (p < 0.05) and DCTE the changes in NOX-1 and NOX-4 (p < 0.05 for both)." (PMID 36139877, 2022). "In addition, two SNPs, GPX3 rs922429 and GPX4 rs2074451 showed protection against obesity classified by BFP." (PMID 32752212, 2020). "In addition, we identified a protective effect of SNPs in GPX3 rs922429 and GPX4 rs2074451 in Mexican children and adolescents, only when obesity was defined under the BFP criterion instead of BMI." (PMID 32752212, 2020). "Moreover, both troglitazone (TZD) treatment and obesity decreased GPX1 and GPX3 protein levels in adipose tissue, being indicative of low contribution of adipose tissue GPX to serum GPX activity." (PMID 32344656, 2020). "Furthermore there was no significant change in the mRNA expression over 48 hours of CD14, endothelin-1 or ACE while there was a marked decrease in FABP-4, GPX-3, and LPL mRNA but enhanced release in obesity." (PMID 20508843, 2010). "Consistently, in drug-naïve T2D patients from the ChiHOPE cohort, lower baseline plasma GPX3 levels were correlated with more adverse metabolic profiles, including lower high-density lipoprotein cholesterol (HDL-C), and higher insulin resistance, circulating lipids and obesity." (PMID 40895323, 2025).
breast carcinoma (27 papers, 2010 to 2025). "Accordingly, low serum Se and SELENOP concentrations as well as low serum GPx3 activity have been associated with higher risk of mortality and recurrence after breast cancer diagnosis." (PMID 37741974, 2023). "Collectively, we demonstrate that GPX3 is markedly downregulated in breast cancer, possesses significant diagnostic and prognostic values and attenuated in vitro growth and metastasis of breast cancer." (PMID 32782436, 2020). "By combination of receiver operating characteristic (ROC) curve analysis, survival analysis and expression analysis, GPX3 was considered as a potential tumor suppressor and a promising diagnostic/prognostic biomarker in breast cancer." (PMID 32782436, 2020). "Several studies have been reported the association between GPX3 expression and its correlation with cancer carcinogenesis including breast cancer." (PMID 33392611, 2020). "All these findings together indicated that only GPX2 and GPX3 possessed significant diagnostic and prognostic values for breast cancer." (PMID 32782436, 2020). "Four potential miRNAs (hsa-miR-324-5p, hsa-miR-328-3p, hsa-let-7a-5p and hsa-miR-449b-5p), which were inversely associated with GPX3 expression in breast cancer, were identified." (PMID 32782436, 2020). "Low expression of GPX3 significantly correlates with high risk of breast cancer local recurrence among early-stage invasive breast cancer patients, regardless of patients' clinic-pathological criteria." (PMID 24790704, 2014). "While we observed few significant associations between selenoprotein genes and breast cancer risk, GPX3 was marginally significant among women with lower NA ancestry and SEPP1 was statistically significant among women with higher NA ancestry." (PMID 24278290, 2013). "GPX3 rs8177447 (p=0.009, padj=0.02) was associated with breast cancer risk for the entire population." (PMID 24278290, 2013). "Based on ARTP results, GPX3 was borderline statistically significantly associated with breast cancer risk for all women and for women with lower levels of NA ancestry specifically." (PMID 24278290, 2013). "Similarly, selenium status biomarkers, including total glutathione peroxidase 3 (tGPX3) activity, have been linked to improved OS and reduced recurrence in breast cancer patients, highlighting the prognostic value of trace elements in cancer biology." (PMID 41479846, 2025). "Notably, these findings suggested that GPX3 was the most potential diagnostic biomarker for patients with breast cancer, with the Area Under Curve (AUC) value being equal to 0.9207." (PMID 32782436, 2020). "Specifically, a previous study demonstrated that overexpression of GPX3 inhibits the progression of breast cancer cells in vitro, which is consistent with our study." (PMID 41020869, 2025). "Two reports on breast cancer showed that the overexpression of GPX3 was negatively correlated with lymph node metastasis." (PMID 37175499, 2023). "SELENOP-aAb along with serum Se, SELENOP and GPX3 activity were determined in serum samples of 1988 patients with a new diagnosis of breast cancer enrolled in the multicentre SCAN-B study." (PMID 35636018, 2022). "GPX3 overexpression inhibited breast cancer growth, colony formation, migration, and invasion in vitro." (PMID 36199800, 2022). "When GPX3 expression in breast cancer cells and tissues was compared to normal controls, it was shown to be low." (PMID 36199800, 2022). "High GPx3 expression is a potential marker for the diagnosis and prognosis and can inhibit the progression in breast cancer, clear cell ovarian cancer hepatocellular carcinoma, cervical cancer and melanoma patients." (PMID 34926458, 2021). "We also found that GPX3 mRNA expression in breast cancer tissues was much lower than that in adjacent matched normal tissues." (PMID 32782436, 2020). "Given the low expression of GPX3 in breast cancer, overexpression technology was used to study GPX3′s functions." (PMID 32782436, 2020).
breast carcinoma (continued). "Next, we confirmed the low expression of GPX3 in breast cancer cells and tissues using qRT-PCR, western blot and IHC, which supported the results of bioinformatic analysis." (PMID 32782436, 2020). "After transfection of GPX3-overexpressed plasmid, GPX3 mRNA and protein expression levels were significantly upregulated in breast cancer cells." (PMID 32782436, 2020). "Taken together, overexpression of GPX3 suppressed in vitro migration and invasion of breast cancer cells." (PMID 32782436, 2020). "The results showed that GPX3 protein expression was significantly decreased in breast cancer tissues." (PMID 32782436, 2020). "CCK-8 assay demonstrated that overexpression of GPX3 markedly suppressed in vitro proliferation of breast cancer cells, MCF-7 and MDA-MB-231." (PMID 32782436, 2020). "To further validate the results from in silico analysis, we detected the mRNA and protein expression levels of GPX3 in breast cancer cells and tissues." (PMID 32782436, 2020). "In summary, our current findings indicate that GPX3 is markedly downregulated in breast cancer, promotes in vitro growth and metastasis of breast cancer cells, and servers as a promising diagnostic or prognostic biomarker for patients with breast cancer." (PMID 32782436, 2020). "GPX3 mRNA and protein were significantly downregulated in two breast cancer cells, MCF-7 and MDA-MB-231, when compared with normal cell, MCF-10A." (PMID 32782436, 2020). "We performed meta-analysis for 15 included studies about GPX3, and found that GPX3 mRNA expression was markedly decreased in breast cancer." (PMID 32782436, 2020). "Taken together, GPX3 was the most potential one among all GPXs family genes in breast cancer and was selected for following research." (PMID 32782436, 2020). "Next, low expression of GPX3 was confirmed in breast cancer cells and tissues when compared with corresponding normal controls." (PMID 32782436, 2020). "Intriguingly, we found that the promoter methylation level of GPX3 was significantly upregulated in breast cancer tissues compared with normal controls." (PMID 32782436, 2020). "By combination of survival and expression analysis, miR-324-5p was considered as the most potential upstream miRNA of GPX3 in breast cancer." (PMID 32782436, 2020). "Subsequently, the function of GPX3 in breast cancer cell growth and metastasis was also investigated." (PMID 32782436, 2020). "qRT-PCR, western blot and immunohistochemistry staining were introduced to validate GPX3 expression in breast cancer." (PMID 32782436, 2020). "Overexpression of GPX3 markedly suppressed proliferation, colony formation, migration and invasion of breast cancer in vitro." (PMID 32782436, 2020). "Wound healing assay was first employed to investigate GPX3′s function in controlling migration of breast cancer cells, and the result demonstrated that overexpression of GPX3 obviously attenuated the migrated ability of breast cancer cells." (PMID 32782436, 2020). "Functional experiments revealed that overexpression of GPX3 significantly inhibited in vitro proliferation, colony formation, migration and invasion of breast cancer cells." (PMID 32782436, 2020). "Collectively, GPX3 mRNA and protein expression levels were significantly downregulated in breast cancer, which was identical with the bioinformatic analytic results." (PMID 32782436, 2020). "In case of breast cancer as well GPX3 was downregulated at mRNA as well as at protein levels in the inflammatory breast cancer as compared with non-IBC." (PMID 30143675, 2018). "Inhibition of GPX3 protein expression in the carcinoma tissues of breast cancer patients was confirmed at mRNA level by using qRT-PCR." (PMID 24790704, 2014). "On the contrary, agarose gel electrophoresis of all GPX3-MSP products breast carcinoma tissue samples showed bands of 200 bp corresponding to both unmethylated and methylated GPX3-MSP products." (PMID 24790704, 2014).
breast carcinoma (continued). "We assessed the GPX3 promoter region methylation in 40 breast cancer tissue samples and 6 normal breast tissue samples." (PMID 24790704, 2014). "The aim of the present study was to investigate GPX3 expression and epigenetic regulation in carcinoma tissues of breast cancer patients' in comparison to normal breast tissues." (PMID 24790704, 2014). "Our results revealed that GPX3 protein level and mRNA were significantly expressed in normal breast tissues and downregulated in breast carcinoma tissues." (PMID 24790704, 2014). "These strengths allowed us to show that both GPX3 and SEPP1 were associated with breast cancer; these associations warrant further study in other populations." (PMID 24278290, 2013). "The two candidates, BTD and GPX3, confirmed by this approach were next tested with immunoblot assay in a blinded set of breast cancer and control to ascertain the markers ability to differentiate the two groups." (PMID 20346108, 2010). "These include apparent decreases in caspase-3 and mmp-9, but increases in cadherin 1, thioredoxin reductase 2, and glutathione peroxidase 3 in the KO mammary carcinomas." (PMID 20932318, 2010). "In the initial stages of biomarker discovery using ICAT and Western blot analysis, we confidently observed that BTD and GPX3 were significantly down-regulated in breast cancer plasma compared to age-matched normal healthy control." (PMID 20346108, 2010). "GPX3 had also been reported to inhibit the progression of breast cancer." (PMID 36845676, 2023). "Previously in the cohort used in this study, serum Se, serum SELENOP concentrations, activity of the serum GPx3 as well as novel autoantibodies targeting SELENOP were shown to be independent predictors of survival after breast cancer diagnosis, outperforming established clinical prognostic markers." (PMID 37741974, 2023). "We compared the effect of GPX3 on lung metastasis in breast cancer in vivo." (PMID 36845676, 2023). "Furthermore, hypermethylation of the GPX3 promoter and suppression of hsa-miR-324-5p release have been identified as probable pathways for GPX3 downregulation in breast cancer." (PMID 36199800, 2022). "Finally, we explored the potential detailed mechanisms responsible for GPX3 downregulation in breast cancer." (PMID 32782436, 2020). "Furthermore, colony formation assay also revealed that GPX3 upregulation led to the inhibition of clonogenic capacity of breast cancer cells." (PMID 32782436, 2020). "By combination of correlation analysis, survival analysis and expression analysis for these miRNAs, miR-324-5p was regarded as the most potential miRNA, which was overexpressed, negatively correlated with GPX3 expression, and possessed poor prognosis in breast cancer." (PMID 32782436, 2020). "The report together with our finding revealed that hypermethylation of GPX3 promoter might be a potential mechanism responsible for GPX3 downregulation in breast cancer." (PMID 32782436, 2020). "ROC curve and survival analysis for GPXs family revealed that some of them might serve as promising diagnostic and prognostic biomarkers for breast cancer, especially GPX2 and GPX3." (PMID 32782436, 2020). "We found that GPX2 and GPX3 were significantly downregulated in breast cancer." (PMID 32782436, 2020). "The engineered hiPSC-MSCs successfully delivered GPx3 to the liver and ameliorated hepatic injury by inhibiting hepatic senescence; this result provides potential therapeutic strategies and prospects for breast cancer treatment." (PMID 32571353, 2020). "The functions of GPX3 in breast cancer cells were successively determined." (PMID 32782436, 2020). "Expression analysis demonstrated the significant low expression of GPX3 in breast cancer." (PMID 32782436, 2020). "Next, the low expression of GPX3 was detected in breast cancer cells and tissues." (PMID 32782436, 2020).